IL1A (interleukin 1 alpha)
Diseases named in the same sentence as IL1A in open-access papers (continued):
Sharing a sentence is not in itself a finding about the gene and the disease.
periodontitis (continued). "The inflammatory markers Interleukin-1 alpha(IL-1α), Tumor Necrosis Factor-alpha (TNF-α), and high sensitive C reactive protein (hsCRP), the hematological analyses, and the histological probes showed a similar and reproducible periodontal inflammation for the molar induced periodontitis model." (PMID 35625362, 2022). "The question rises here is that whether these biomarkers (TNF-α and IL-1α) can have relationship with success rate of non-surgical treatment for chronic periodontitis." (PMID 29238418, 2017). "Because it has been reported that IL-1α knockdown may inhibit the circuits between inflammatory processes and bone resorption, AAV-sh-Atp6v1c1 treatment can interfere with this positive feedback also and reverse bone resorption in the progression of periodontitis." (PMID 26274612, 2015). "The results support the hypothesis that proinflammatory cytokines, including IL-1α, IL-1β and IL-6, are likely to be involved in the pathogenesis of periodontitis and are good markers to evaluate the success of nonsurgical therapy in disease sites of patients with periodontitis." (PMID 24944641, 2014). "The aim of the present study was to quantify the total levels of interleukin (IL)-1α, -1β, -6, -10 and tumour necrosis factor (TNF)-α in gingival crevicular fluid (GCF) of chronic periodontitis patients prior to and following nonsurgical periodontal therapy." (PMID 24944641, 2014). "In the present study, the total levels of IL-1α, -1β and -6 in the GCF of disease sites in chronic periodontitis patients decreased in response to nonsurgical therapy." (PMID 24944641, 2014). "The results indicating a decrease in the levels of the proinflammatory cytokines, IL-1α, -1β and -6, but not IL-10 or TNF-α, in the GCF of patients with chronic periodontitis, confirm the observations of previous studies." (PMID 24944641, 2014). "The aim of the present exploratory subanalysis was to evaluate the role of the IL-1A −889, IL-1B +3954, IL-4 −34, IL-4 −590, GATA-3 IVS4 +1468 and COX-2 −1195 gene loci in patients with periodontitis after a non-surgical periodontal therapy with or without additional adjunctive systemic antibiotics." (PMID 35806269, 2022).
atherosclerosis (90 papers, 2009 to 2025). A disease characterized by the build-up of fatty material and calcium deposition in the arterial wall resulting in partial or complete occlusion of the arterial lumen. "IL-1α in macrophage is an important cytokine regulating the development of atherosclerosis, over-representation of IL1A gene was associated with the coronary artery disease." (PMID 37292135, 2023). "Cardiovascular (CV) risk factors (i.e., obesity, diabetes, hypertension, and atherosclerosis) are associated with the inflammatory pathway mediated by IL-1α, IL-6, and IL-8." (PMID 36982253, 2023). "IL-1α is released by necrotic cells and promotes inflammation and senescence, both of which are associated with atherosclerosis." (PMID 37446157, 2023). "IL-1α can be used as the target of treatment in atherosclerosis despite that a specific block of IL-1α predisposes patients to more severe infections compared with IL-1β inhibition." (PMID 37600028, 2023). "Overall, senescent VSMCs can induce persistent inflammation associated with atherosclerosis by exhibiting an IL-1α-driven SASP and inducing a pre-atherosclerotic condition in neighboring cells." (PMID 36082127, 2022). "For example, the SASP directly drives inflammation through IL-1α translocation to the cell surface and activates neighbouring VSMCs, ECs and macrophages, causing the spread of inflammation and promoting atherosclerosis by secondary pro-inflammatory cytokines." (PMID 35642067, 2022). "Yet, a substantial body of evidence indicates the potential of IL-1α inhibition in reducing thrombotic complications of atherosclerosis and in cardiovascular conditions associated with cell death such as myocardial ischemic injury." (PMID 33924019, 2021). "Secondary necrosis of apoptotic VSMCs promotes the release of both IL-1α and IL-1β, which induces the surrounding viable VSMCs to produce proinflammatory cytokines, thus causing a chronic inflammation associated with atherosclerosis." (PMID 35008765, 2021). "The reduction in Il1a expression is of interest since IL-1α was strongly implicated in the pathophysiology of atherosclerosis associated with foamy macrophage development in oleate-fed mice." (PMID 32796836, 2020). "After lethally irradiated bone marrow was reconstituted with wild-type, NLRP3-, ASC-, or IL1α/β-deficient bone marrow, mice had lower levels of IL-18 and IL-1 family cytokines and showed decreased atherosclerosis." (PMID 32596261, 2020). "Association study showed that the TT genotype and T allele of IL-1α-889 C/T were significantly associated with IS of a large artery atherosclerosis (LAA) (TT: OR = 2.01, 95% CI = 1.34–3.0, and P < 0.001; T: OR = 1.44, 95% CI = 1.18–1.78, and P = 0.001)." (PMID 24063019, 2013). "In atherosclerosis IL-1α has also been implicated in the plaque stability and outward vessel remodelling." (PMID 23398985, 2013). "Interleukin-1-alpha, identified as a risk factor, may promote endothelial dysfunction and vascular inflammation, which are critical in atherosclerosis progression seen in PAD." (PMID 39221259, 2024). "In this way, senescentVSMCs develop an inflammatory, senescence-associated secretory phenotype drivenby IL-1α that may contribute to atherosclerosis." (PMID 39077721, 2022). "Reduced atherosclerosis has been reported in IL-1α-deficient mice." (PMID 29329335, 2018). "Furthermore, serum amyloid A protein, an inflammatory marker in atherosclerosis, was reduced despite higher total cholesterol concentrations in IL-1α deficient mice fed with high-fat diet." (PMID 27456968, 2016).
atherosclerosis (continued). "TNF-α, IL-1α and IL-12 are known as pathogenic factors during the development of atherosclerosis." (PMID 24708830, 2014). "Meanwhile, further evidence supports that the upregulation of RCN2 in atherosclerosis, as well as the ability of IL-1A to mitigate the progression of atherosclerosis, can both serve as potential biomarkers for CAD." (PMID 39742022, 2024). "Inflammatory macrophage cluster identified from an atherosclerosis mouse model showed high-level expression of various genes previously assigned to a pro-atherogenic role (e.g., Ccl3, Il1b, Il1a, Nlrp3, Cebpb, Egr1, and Phlda1)." (PMID 38149246, 2023). "Similar effects on atherosclerosis were shown by the administration of Anakinra, which is a recombinant human IL-receptor antagonist (IL-Ra) that blocks signaling by both IL-1β and IL-1α." (PMID 37446157, 2023). "Although Il1a knock out animals show greatly reduced atherosclerosis development compared with PCSK9-WT animals, macrophage infiltration per plaque is unchanged." (PMID 37701434, 2023). "The present study provides evidence for a significant contribution of IL-1α during the development of atherosclerosis." (PMID 37701434, 2023). "The results highlight the importance of IL-1α on the cell surface of circulating leucocytes for the development of atherosclerosis." (PMID 37701434, 2023). "IL-1α has also been proven to induce atherosclerosis, as IL-1α-ablated bone marrow transplantation into LDL receptor-null mice impairs atherosclerosis." (PMID 38270118, 2023). "Myristoylation and translocation of IL-1α to the cell surface in myeloid cells facilitates leukocyte adhesion and contributes to the development of atherosclerosis." (PMID 37701434, 2023). "In contrast, IL-1α appeard to be more critical in early atherosclerosis due to its influence on arterial outward remodelling." (PMID 37701434, 2023). "It is conceivable that apoptosis of SMCs resulting from polyploidization causes the release of proinflammatory cytokines and many other factors, including IL-1α and IL-1β, consequently accelerating atherosclerosis in the presence of atherogenic factors." (PMID 36750553, 2023). "The potential for thrombin activation of IL-1α is particularly interesting in the contextof atherosclerosis and other vascular diseases." (PMID 37309666, 2023). "As downstream effectors of inflammasomes, it has been reported that IL-1α played a key role in the early stage of atherosclerosis, while IL-1β induced inflammation in advanced atherosclerosis in mice." (PMID 35464402, 2022). "The role of IL-1α in atherosclerosis is has been less straightforward, thus its inhibition is not broadly attempted." (PMID 36555579, 2022). "One explanation of this is the fact that based on the mouse model (ApoE–/–), IL-1α is primarily responsible for atherosclerosis." (PMID 36082127, 2022). "This was explained by the fact that in the mouse model used (ApoE−/−), IL-1α mostly contributes to the development of atherosclerosis." (PMID 32648087, 2021). "Previous studies have found that senescence aortic smooth muscle cells promote the development of atherosclerosis by secreting SASP (IL-1α)." (PMID 33897463, 2021). "IL-1α and β have countless physiological effects known to play a role in the pathogenesis of numerous diseases including atherosclerosis, myocardial infarction, and ischemic stroke." (PMID 33770265, 2021). "As both IL-1α and IL-1β cytokines were found to be elevated in atherosclerotic plaques, their contribution to atherosclerosis development has been extensively investigated during the past decade." (PMID 33562334, 2021). "The studies in animal models of atherosclerosis demonstrated an increased expression of IL-1α and IL-1β mRNAs in the aortas of animals fed with cholesterol." (PMID 32587660, 2020).
atherosclerosis (continued). "IL-1 pathway seems to play an important role in atherosclerosis, with IL-1α and/or β promoting the expression of VCAM-1, ICAM-1, and E-selectin, with increased endothelial cell permeability, adhesion molecules expression." (PMID 31186952, 2019). "In this study, the gender differences in circulating IgG antibodies to inflammatory cytokines were observed, so that up-regulation of anti-TNFα, anti-IL1α, and anti-IL1β IgG levels were more likely to occur in female than male patients with atherosclerosis." (PMID 30479572, 2018). "In this study, we found that plasma anti-TNFα and anti-IL1α IgG levels were significantly increased in patients with atherosclerosis compared with control subjects, and an increase in anti-IL1β IgG level was found in female patients." (PMID 30479572, 2018). "Although circulating levels of anti-TNFα and anti-IL1α IgG antibodies were significantly increased in atherosclerosis, ROC curve analysis revealed relatively low sensitivity." (PMID 30479572, 2018). "Ten key regulated genes (including Pla2g2f, Il1f9, Col1a1, Col1a2, and Col3a1 in the brain, while SELP, SELE, IL6, and IL1A in the myocardium, and Tnfrsf12a in both) are correlative with atherosclerosis signaling and inflammatory response." (PMID 29681850, 2018). "The differential induction and distinct roles of IL-1α and IL-1β in fat-induced vascular responses and atherosclerosis have recently been highlighted." (PMID 29329335, 2018). "The specific role of the two IL‐1α and IL‐1β isoforms in atherosclerosis development is still under debate." (PMID 28409825, 2017). "PCR-Array: mRNA expression of 16 of 84 atherosclerosis-related genes were significantly regulated at least 2-fold by IL-1α alone in comparison to control (p<.05), ranging from 8.3-fold (SELPLG) to 108.4-fold (TGFB2) up-regulation." (PMID 28323859, 2017). "IL-1α is associated with CVD and can contribute to atherosclerosis through the expression of cell-adhesion molecules (vascular cell-adhesion molecule-1 and intracellular adhesion molecule-1)." (PMID 25648164, 2015). "IL-1α and IL-1β contribute to the development of vascular damage and atherosclerosis by stimulating cell proliferation and differentiation and the release of matrix-degrading enzymes." (PMID 24063019, 2013). "Monocytes, their progeny such as dendritic cells and osteoclasts and products including tumor necrosis factor (TNF)-α, interleukin (IL)-1α and IL-1β play important roles in cancer, inflammation, immune response and atherosclerosis." (PMID 19715605, 2009). "This is in agreement with previous studies that showed decreased atherosclerosis in IL-1β−/− and IL-1α−/− mice fed a high cholate diet and with data from a heterozygote Apoe−/− model." (PMID 19347044, 2009). "The proinflammatory IL-1-alpha (IL-1α) is enhanced in atherosclerosis." (PMID 38469142, 2024). "The role of cell-surface (cs) IL-1α in the initiation of atherosclerosis." (PMID 37701434, 2023). "Aside from IL-1β, IL-1α plays an equally important role in atherosclerosis." (PMID 37446157, 2023). "Gene regulatory network analysis identified specific liver regulators related to lipid metabolism (SC5D, LCAT and HMGCR), inflammation (IL1A) and fibrosis (PDGF, COL3A1), linked to a set of aorta target genes related to vascular inflammation (TNFA) and atherosclerosis signaling (CCL2 and FDFT1)." (PMID 35897797, 2022). "Using this method, we identified several hepatic regulators related to lipid metabolism (SC5D, LCAT and HMGCR), inflammation (IL1A) and fibrosis (PDGF and COL3A1) that were linked to a set of aorta target genes related to vascular inflammation (TNFA) and atherosclerosis signaling (CCL2 and FDFT1)." (PMID 35897797, 2022).
atherosclerosis (continued). "Previous study has verified that elevated SASP mRNA expression (including Il-1α, Tnf-α, Ccl2, Mmp12, and Mmp13) significantly increases in senescent foamy macrophages during atherosclerosis, which has the similar characteristics of SASP in senescent macrophages during lung fibrosis." (PMID 34023858, 2021). "IL-1α is unregulated in cholesterol fed mice and can stimulate atherosclerosis." (PMID 34445361, 2021). "Canakinumab, a fully human IL-1β neutralizing monoclonal antibody, emerged as a potentially more viable candidate both because of the specific role IL-1β signaling plays in potentiating atherosclerosis and because it would leave host immune function via IL-1α intact." (PMID 30873416, 2019). "IL-1β represents the tip of the iceberg; there are several other potential inflammatory mediators that could be directly targeted to halt atherosclerosis progression, such as by directly targeting the inflammasome, IL-1α, IL-6, IL-18, and IL-33, among others." (PMID 31672136, 2019). "Firstly, IL-1α played an important role in atherosclerosis development in the ApoE−/− mice model." (PMID 31354731, 2019). "Overall, it is intriguing that IL-1α may exert effect on progression of atherosclerosis in Rgp44-immunized mice whereas the anti-inflammatory cytokines IL-5 and IL-10 are crucial for possible atheroprotection in Pg-immunized mice." (PMID 29329335, 2018). "In addition, patients with atherosclerosis had a significantly higher level of circulating IgG against IL1α antigens than control subjects (t = 3.084, p = 0.002) and female patients mainly contributed to the significant change (t = 2.964, p = 0.003)." (PMID 30479572, 2018). "IL-1α also contributes to atherogenesis, as transplantation of IL-1α-deficient bone marrow into mice lacking the LDL receptor leads to reduction of atherosclerosis." (PMID 29511093, 2018). "In addition, we found that MCP-1, IL-1α and IL-6, which all play an important role in atherosclerosis, were also induced by CC stimulation in primed macrophages." (PMID 24686534, 2014). "Furthermore, platelets also contain IL-1α, and platelet-derived IL-1α has been described to be important in brain injury in stroke models and in atherosclerosis." (PMID 23847614, 2013). "Importantly, these data highlight the importance of IL-1α in atherosclerosis and the need for detailed understanding of the mechanisms of the translocation and presentation of IL-1α to the plasma membrane as a target for novel therapies, such as myristoylation inhibitors." (PMID 37701434, 2023). "Atherosclerosis may be targeted by blocking IL-1α, a potential source of chronic inflammation." (PMID 36082127, 2022). "Thus, the role of IL-1α inhibition in atherosclerosis is uncertain." (PMID 36555579, 2022). "Here, the inflammatory molecules in our panel that showed the most significance in PD, and particularly IL-1α, IL-1β, IL-17A, and TNF-α are all known to be dysregulated in cardiovascular disease and their presence in circulation might be linked to atherosclerosis." (PMID 31507404, 2019). "The common mechanisms shared in both are linked with atherosclerosis signaling and inflammatory response with at least the following target genes: Tnfrsf12a, Pla2g2f, Il1f9, Col1a1, Col1a2, and Col3a1 in brain, while Tnfrsf12a, SELP, SELE, IL6, and IL1A in myocardium." (PMID 29681850, 2018).